ENSG00000212567
Synonyms: LOC124900202
Gene: Small nucleolar RNA gene on chromosome 5 (40,790,077 to 40,790,204, reverse strand). Ensembl gene ENSG00000212567.
Gene Ontology:
Biological process: RNA processing
Cellular component: nucleolus
Homologues: Paralogues in human: SNORA57 (77% identical).